FGF1 (fibroblast growth factor 1)
Diseases named in the same sentence as FGF1 in open-access papers (continued):
Sharing a sentence is not in itself a finding about the gene and the disease.
type 2 diabetes (26 papers, 2015 to 2026). "Here, we present engineered variants of FGF1 designed to dissociate its potent glucose-lowering effects from its undesired proliferative activity, aiming for a future therapeutic agent for type 2 diabetes." (PMID 41520078, 2026). "Our data establish adipocyte HS composition as a determinant of Type 2 diabetes susceptibility and the critical dependency of the endogenous adipocyte FGF1 metabolic pathway on HS." (PMID 41072794, 2025). "In rodent models of type 2 diabetes, a single intracerebroventricular (icv) injection of fibroblast growth factor 1 (FGF1) induces sustained remission of hyperglycemia." (PMID 41371441, 2026). "Our findings highlight a successful strategy to uncouple the therapeutic benefits of FGF1 from its mitogenic side effects, offering promising, stable, and safe protein-based drug candidates for type 2 diabetes treatment." (PMID 41520078, 2026). "While further preclinical and clinical assessments are warranted to fully elucidate long-term safety and efficacy, these engineered FGF1 proteins represent highly promising candidates for a new generation of protein-based drugs to combat type 2 diabetes." (PMID 41520078, 2026). "FGF1 is known to play a key role in metabolic diseases and has potential therapeutic applications for conditions such as type 2 diabetes." (PMID 41430037, 2025). "Our findings are consistent with previous findings that the HOMA-B was lower in participants with higher FGF1 levels among patients newly diagnosed with type 2 diabetes and healthy controls." (PMID 37284218, 2023). "In the present study, db/db mice had elevated plasma TG levels, a common feature of dyslipidemia accompanying with type 2 diabetes; this effect was diminished by FGF1 treatment." (PMID 32194395, 2020). "In rodent models of type 2 diabetes, sustained remission of hyperglycemia can be induced by FGF1 action in the mediobasal hypothalamus." (PMID 32895383, 2020). "This discovery uncovers an unexpected, neomorphic insulin-sensitizing effect of FGF1 to treat type 2 diabetes and expands the functions of this classically known mitogen." (PMID 31920680, 2019). "Treatment with FGF1 restores normal blood sugar levels in a murine model of type 2 diabetes, and FGF1 knockout mice develop aggressive type 2 diabetes and aberrant adipose expansion." (PMID 26375667, 2015). "Notably, it has been demonstrated that the serum level of FGF1 is significantly elevated in newly diagnosed type 2 diabetes and correlated with metabolic parameters, such as fasting plasma glucose and body mass index." (PMID 35011683, 2021). "Furthermore, it was demonstrated that a single intracerebroventricular FGF1 injection can reduce the disease progress in rodent models of type 2 diabetes." (PMID 35011683, 2021). "FGF1 is a promising agent for the treatment of type 2 diabetes by improving insulin sensitivity." (PMID 34149434, 2021). "The significant mitogenic activity of FGF1 remains a primary concern, potentially limiting its therapeutic application in type 2 diabetes (T2D) treatment." (PMID 41520078, 2026). "Based on its angiogenic function, FGF1 is a major player in wound healing; it has decreased gene expression in early phases of wound healing in diabetic patients, and it has a proven effect on reepitelization in NONcNZO10/LtJ mouse (model for impaired wound healing in type 2 diabetes)." (PMID 30622976, 2018). "Fibroblast growth factor 1 (FGF1), a well-characterized member of the FGF family, effectively lowers blood glucose levels in animal models of type 2 diabetes by stimulating glucose uptake." (PMID 41520078, 2026). "In rodent models of type 2 diabetes (T2D), sustained remission of hyperglycemia can be induced by a single intracerebroventricular (icv) injection of fibroblast growth factor 1 (FGF1), and the mediobasal hypothalamus (MBH) was recently implicated as the brain area responsible for this effect." (PMID 32895383, 2020).
ovarian carcinoma (22 papers, 2011 to 2025). A malignant neoplasm originating from the surface ovarian epithelium. "FGF1 expression and secretion are increased in ovarian cancer associated fibroblasts (CAFs), which, when cultured with the SKOV3 human ovarian cancer cell line, increases ERK1/2 activity through activation of FGFR4." (PMID 34068954, 2021). "FGF1 amplification in ovarian cancer has been associated with promoting angiogenesis, reduced disease-free progression and overall survival." (PMID 34068954, 2021). "Compared with other family members, FGF1 genetic variation has the most significant correlation with an increased risk of ovarian cancer." (PMID 32660514, 2020). "FGF1 expression in ovarian cancer is associated with chemotherapy resistance." (PMID 34068954, 2021). "Elevated FGF1 levels are associated with increased angiogenesis and decreased survival in serous ovarian adenocarcinoma, and is a potential therapeutic target for ovarian cancer." (PMID 32615540, 2020). "FGF1 promotes cell proliferation, migration, and invasion in different cancers, such as ovarian cancer, oral squamous cell carcinoma, and colorectal cancer." (PMID 38764020, 2024). "Further, several studies reported that the FGFR4 isoform is overexpressed in ovarian cancer patients (in advanced stages) and mainly interacts with FGF1." (PMID 39766329, 2024). "Overexpression of FGF1 can aggravate certain cancers such as ovarian cancer, non-small cell lung cancer, colorectal cancer, and pancreatic cancer." (PMID 39766329, 2024). "It has been reported that FGF1 upregulation stimulates angiogenesis and reduces overall survival in patients with ovarian cancer." (PMID 38764020, 2024). "Consistent with our findings, others have confirmed that FGF1 is more highly expressed in platinum-resistant compared to drug-sensitive ovarian cancers." (PMID 35778553, 2022). "Pharmacological inhibition of FGF signalling reversed drug resistance in immortalised cell lines and in primary cell lines from drug-resistant ovarian cancer patients, while FGF1 over-expression induced resistance." (PMID 35778553, 2022). "CAFs promote ovarian cancer cell proliferation, migration, and invasion through the paracrine FGF-1 factor." (PMID 30380628, 2018). "The high copy numbers of FGF1 have been found in prostate, non-small-cell lung, breast and ovarian cancers." (PMID 26183397, 2015). "Similarly, resistance to cisplatin and carboplatin was induced by heterologous FGF1 expression in chemonaive SK-OV-3 and CaOV3 ovarian cancer cells." (PMID 35778553, 2022). "Our study suggested that MIR502 had a counter-regulatory expression effect on FGF1, and a low level of MIR502 expression increases FGF1 expression in ovarian cancer, which may lead to OC development and platinum chemotherapy resistance." (PMID 32660514, 2020). "Furthermore, the fact that in vivo suppression of tumorigenicity was lost with P95R indicated the biological importance of the AXL pathway in ovarian cancer despite an intact FGFR1/FGF1 axis." (PMID 31316070, 2019). "More generally, this study provides the molecular basis for the comprehension of the role of FGF1 in the resistance to chemotherapy in ovarian cancers and could potentially be extended to other cancers overexpressing FGF1." (PMID 29467390, 2018). "The FGF-1/FGFR-4 signaling axis regulates the stromal microenvironment in ovarian carcinomas." (PMID 30380628, 2018).
ovarian carcinoma (continued). "In addition, proliferative CAFs were previously reported to secrete FGF1, which promotes ovarian cancer cell proliferation and invasion, implying that Branch 5 CAFs may promote tumor progression via similar mechanisms." (PMID 35884546, 2022). "Therefore, the regulation of FGF1 by different mechanisms may play an important role in the development of ovarian cancer." (PMID 32660514, 2020). "In ovarian cancer, the WNT7A-β-catenin axis can regulate FGF1 expression in cancer cells by interacting with TCF-binding elements of the FGF1 promoter." (PMID 39766329, 2024). "Fibroblast growth factor (FGF-1) and interleukine 1 (IL1) are also expressed in both endometriosis and ovarian cancer, suggesting a common mechanism of action towards the malignant transformation." (PMID 38673556, 2024). "We have previously shown that individuality in fibroblast growth factor 1 (FGF1) expression significantly inversely influences both progression-free and overall survival in ovarian cancer patients." (PMID 35778553, 2022). "In this study, we show that FGF1 favors survival of COV434 cells upon treatment with etoposide and cisplatin, two common chemotherapeutic molecules used for ovarian cancer." (PMID 29467390, 2018). "CAF markers that have been identified in ovarian cancer include α-SMA, FAP, FSP1, and FGF-1." (PMID 33808627, 2021). "We investigated the relationship between the three subtypes and various well‐known oncogenic genes and tumour suppressors in ovarian cancer from cBioPortal and found EIF5A2 (P < 0.001), FGF1 (P < 0.001) and EGFR (P = 0.002) were highly expressed in the CAFs‐immune subtype." (PMID 33522069, 2021). "We now confirm that introduction of FGF1 to drug-sensitive cells confers resistance, and that resistance is reversible by co-administration of pharmacological FGFR inhibitors in both immortalised cell lines and primary ascites-derived cell lines from drug-resistant ovarian cancer patients." (PMID 35778553, 2022).
glioma (21 papers, 2014 to 2025). A benign or malignant brain and spinal cord tumor that arises from glial cells (astrocytes, oligodendrocytes, ependymal cells). "In glioblastoma, RFX1 was shown to negatively regulate the self-renewal capacity of glioma stem cells through direct FGF1 suppression, and to inhibit tumor invasiveness via downregulation of CD44." (PMID 41425715, 2025). "This small antibody is based on hybridoma derived from mouse immunized with FGF1 and inhibits growth of breast and glioma tumors in vitro and in vivo." (PMID 30134556, 2018). "The TRPV2 interactome showed a high association with early glia-related neoplasms, especially glioma/glioblastoma, being ABR, FGF1, KCNJ10, PEBP1, PLP1, SDC3, and TRPV2, the genes associated to these brain neoplasms." (PMID 29719613, 2018). "As FGF1, which plays an important role in glioma by activating PI3K/AKT and MEK 1/2 pathways is a target of miR-326, an increased expression of miR-326 reduced FGF1 expression level." (PMID 30583549, 2018). "FGF1 expression was significantly up-regulated in GT and two glioma cell lines compared with that in ST and NBTs, respectively." (PMID 26183397, 2015). "We then explored the possible biological significance of FGF1 in glioma cells, and found that FGF1 over-expression promoted cell proliferation, migration and invasion, as well as inhibiting the cell apoptosis and cell cycle arrests in G0/G1 phase." (PMID 26183397, 2015). "The further study showed that miR-326 played a tumor-suppressive role by down-regulating FGF1 in glioma cell." (PMID 26183397, 2015). "Our results further demonstrated that miR-326 inhibited the proliferation, migration and invasion, induced the apoptosis and cell cycle arrest in G0/G1 phase by targeting the 3′-UTR of FGF1 in human glioma cells." (PMID 26183397, 2015). "For example, comparing intracranial glioma CSF to lumbar NPH samples might suggest that fibroblast growth factor-1 (FGF1) is elevated in gliomas (C. Riviere-Cazaux, T. Burns, personal communication, November 5, 2024)." (PMID 39786477, 2025). "This indicates FGF1 levels in part reflect the fact that this protein is an intracranial CSF-associated protein as opposed to a purely glioma-specific readout." (PMID 39786477, 2025). "However, paired intracranial and lumbar glioma CSF analyses demonstrate that FGF1 is more abundant in intracranial than lumbar CSF in gliomas, as it is in intracranial versus lumbar CSF in NPH." (PMID 39786477, 2025). "Studies have shown that HOTAIR promotes development of glioma by inhibiting Mir-326 and further promoting the expression of fibroblast growth factor 1 (FGF1), which plays a significant carcinogenic role in tumorigenesis by activating the MEK1/2 and PT3K/AKT pathways." (PMID 35935338, 2022). "Moreover, HOTAIR promoted the development of glioma and the expression of fibroblast growth factor 1 (FGF1), which promotes tumorigenesis by activating the PT3K/AKT pathway tumorigenic function." (PMID 35813070, 2022). "Transcriptomic analyses showed an increased expression of ABCG2, ALDH1, FGF1 stem cell markers in the pale region, when compared to the tumor mass, suggesting the presence, in the infiltrating front of the tumor, of a glioma stem cell (GSC) population possibly responsible for tumor recurrence." (PMID 33066172, 2020). "For instance, HOTAIR, a well-known lncRNA could inhibit the expression of FGF1 by regulating miR-326 in human glioma, and also functioned as a competing endogenous RNA to regulate HER2 expression by sponging miR-331-3p in promoting gastric cancer." (PMID 27267902, 2016). "Furthermore, the FGF1 expression was positively correlated with the histopathological grades of glioma." (PMID 26183397, 2015). "In our present study, the FGF1 expression was up-regulated in human glioma tissues and cell lines." (PMID 26183397, 2015). "Moreover, over-expressed miR-326 reduced the FGF1 expression which played an oncogenic role in glioma by activating PI3K/AKT and MEK 1/2 pathways." (PMID 26183397, 2015).
glioma (continued). "In brief, the miR-326 over-expression induced by the knockdown of HOTAIR could down-regulate the FGF1 expression that acted as an oncogenic factor in human glioma." (PMID 26183397, 2015). "Taken together, knockdown of HOTAIR up-regulated miR-326 expression, and further inducing the decreased expression of FGF1, these results provided a comprehensive analysis of HOTAIR-miR-326-FGF1 axis in human glioma and provided a new potential therapeutic strategy for glioma treatment." (PMID 26183397, 2015). "FGF1 expression in human glioma tissues and cell lines was analyzed by Western blot." (PMID 26183397, 2015). "Thus, HOTAIR/miR-326/FGF1 plays an important role in glioma." (PMID 30583549, 2018). "Furthermore, our study showed that FGF1 played an oncogenic role in human glioma cells." (PMID 26183397, 2015). "Therefore, FGF1 might be one of the factors that were responsible for the malignancy of glioma." (PMID 26183397, 2015). "The result of MPI siRNA knockdown on cell migration was also investigated in the SKMG-3 glioma cell line, and like the U-251 cells, we found impaired migration after MPI knockdown with partial rescue by FGF1." (PMID 25314669, 2014). "Given that a pro-tumorigenic role for acidic-FGF1 has not previously been established for glioma, we evaluated the effect of recombinant FGF1 on 320-GSCs in growth factor depleted media, revealing a dose-responsive increase in 320-GSC growth." (PMID 38528608, 2024). "Over-expression of miR-326 inhibited FGF1 expression by targeting its 3′-UTR and further blocked the activity of PI3K/AKT and MEK1/2 pathways, leading to the inhibition of malignant behaviors of glioma cells." (PMID 26183397, 2015). "Therefore, the reduced FGF1 induced by miR-326 over-expression could attenuate the activity of PI3K/AKT and MEK 1/2 pathways to inhibit the malignant behaviors of glioma cells." (PMID 26183397, 2015).
Hyperglycemia (19 papers, 2012 to 2026). An increased concentration of glucose in the blood. "In the current study, FGF1 administration reduced hyperglycemia, suggesting that hyperglycemia may be also the key caused factor for DICD occurrence and development." (PMID 32460803, 2020). "A single intracerebroventricular injection of FGF1 at low doses sustains remission of hyperglycemia in obese mice and diabetic rats." (PMID 40243151, 2025). "Injection of fibroblast growth factor 1 (FGF1) can improve hyperglycemia, with the main target being glial cells in the mediobasal hypothalamus." (PMID 40452923, 2025). "As an example, a single intracerebroventricular (icv) injection of fibroblast growth factor 1 (FGF1) can normalize hyperglycemia for weeks or months in rodent models of T2D." (PMID 40371641, 2025). "FGF1’s central effect in lowering hyperglycemia occurs through the induction of hepatic glucokinase, which increases hepatic glucose uptake." (PMID 40243151, 2025). "In the current work we report not only that hyperglycemia is normalized comparably by icv FGF1 and AgRP neuron inactivation, but that in each case the effects are sustained for weeks or months." (PMID 40371641, 2025). "Previous studies suggest that fibroblast growth factor-1 (FGF-1) can mitigate hyperglycemia and protect tissues from HG-induced damage." (PMID 38542166, 2024). "Increased activity of NPY/AgRP neurons in the hypothalamic arcuate nucleus (ARC) is implicated in the pathogenesis of hyperglycemia in these animals, and the ARC is a key brain area for the antidiabetic action of FGF1." (PMID 35917179, 2022). "Myriad studies have characterized the long-term effects of FGF1 on hyperglycemia and food intake, with differing results depending on the animal model and route of administration." (PMID 34987476, 2021). "In summary, our findings expand the notion that FGF1 controlled hyperglycemia and normalized blood glucose levels in db/db mice." (PMID 32194395, 2020). "However, the specific neuronal types and brain regions involved in FGF1’s central anti-hyperglycemia actions remain unidentified." (PMID 40243151, 2025). "Pronounced hyperglycemia and IR were noted in FGF1 knockout mice that consumed high-fat foods, suggesting that FGF1 may play a regulatory role in nutritional homeostasis." (PMID 36293317, 2022). "However, there have only been a few studies on FGF1-regulated angiogenesis and hyperglycemia in diabetic stroke." (PMID 34025437, 2021). "Central administration of fibroblast growth factor-1 (FGF1) results in long-lasting resolution of hyperglycemia in various rodent models, but the pre- and postsynaptic mechanisms mediating the central effects of FGF1 are unknown." (PMID 34987476, 2021). "While the mechanism by which FGF1 induces the remission of hyperglycemia is unknown, there is sufficient evidence to suggest that its actions involve interplay between the brain and periphery, leading to long-term changes in hepatic and pancreatic function." (PMID 34987476, 2021). "The effect of FGF1 was partially reversible in most cells suggesting it is unlikely that the acute electrophysiological response of ARH-POMC neurons alone is responsible for sustained improvements in hyperglycemia." (PMID 34987476, 2021). "Here, we had determined FGF1 expression in hippocampus under hyperglycaemia condition." (PMID 32460803, 2020). "FGF1 has dual function of normalizing hyperglycemia and neuroprotection." (PMID 32460803, 2020). "FGF1, is an autocrine/paracrine regulator whose binding to heparan sulphate proteoglycans, plays a role on proliferation, neuroprotection and effectively normalizing hyperglycemia in T2D mice." (PMID 30320493, 2018). "Fibroblast growth factor 1 (FGF1) has dual function of neuroprotection and normalizing hyperglycemia." (PMID 32460803, 2020).